TLR4 (toll like receptor 4)
Diseases named in the same sentence as TLR4 in open-access papers (continued):
Sharing a sentence is not in itself a finding about the gene and the disease.
endotoxemia (continued). "In LPS induced endotoxemia, METTL3 directly modulates m6A on TLR4 mRNA, promoting its translation and stabilizing the transcript, which elevates TLR4 protein expression and activates the neutrophil TLR4 signaling pathway." (PMID 40963968, 2025). "Cinnamaldehyde inhibits intracellular ROS production and suppresses TLR4 and NOX4 during LPS-induced endotoxemia." (PMID 40572518, 2025). "Subsequently, LPS binds to toll-like receptor 4 (TLR4) on the target tissue, thereby inducing endotoxemia and eliciting a systemic inflammatory response." (PMID 39524709, 2024). "A previous animal study showed that the M1 to M2 (M1/M2) macrophage ratio had a positive correlation with plasma LPS binding protein levels and TLR4 and CD14 mRNA levels, supporting the role of endotoxemia in the induction of liver inflammation." (PMID 39200311, 2024). "In lipopolysaccharide (LPS)-induced endotoxemia, METTL3 controls neutrophil release from the bone marrow into the circulation in a TLR4-signaling-dependent mechanism involving surface expression of CXC chemokine receptor 2 (CXCR2)." (PMID 39686999, 2024). "In endotoxemia, METTL3-mediated m6A-modification of Tlr4 showed increased translation and slowed degradation, which was critical for neutrophil activation." (PMID 37486903, 2023). "The observed transcriptional response is also in line with evidence linking hLF-function to basal TLR-4 activation via its carbohydrate chains and suppression of TLR4 signaling upon endotoxemia through its peptide moiety." (PMID 37868991, 2023). "These processes were also observed in a murine model of endotoxemia, highlighting NET formation upon platelet TLR4 activation in liver sinusoids and pulmonary capillaries as an effective, threshold-induced mechanism for bacterial trapping." (PMID 35741086, 2022). "Our lab further demonstrated that EGFR and TLR4 co-regulate macrophage activation in endotoxemia and EGFR phosphorylation is necessary to increase TLR4 cell surface expression and signal transduction." (PMID 36344490, 2022). "Microbial imbalance and endotoxemia are able to promote the expression of pro-inflammatory cytokines, such as IL6, TNF-α, IL-1, and plasminogen activator inhibitor-1 in a TLR-4 dependent manner." (PMID 33536239, 2021). "This process is manifested by endotoxemia and increased production of proinflammatory cytokines (TNF-alpha, IL-1, IL-6) by immune cells as a result of binding of LPS to the CD14/TLR4 complex on their surface." (PMID 35056501, 2021). "All these results indicate that TLR4 plays an significant role in parthanatos in the presence of LPS, and PARP-1 probably represents a latent new target for the treatment of endotoxemia." (PMID 34282120, 2021). "The cell membranes of these bacteria contain a lipopolysaccharide (LPS) that activates Toll-like receptor 4 (TLR4), inducing endotoxemia." (PMID 32252416, 2020). "Activation of the TLR4/TRAF6/NF-κB pathways was involved in the occurrence and development of intestinal mucosal injury and endotoxemia in mice with OJ." (PMID 31671112, 2019). "The activation of TLR4 signal pathway started from recognizing particular TLR ligands including LPS and LPS/TLR4 signaling, has been proved to be involved in endotoxemia induced multiple organ dysfunction." (PMID 28059131, 2017). "Additionally, another study indicated that the administration of TAK-242, a Toll-like receptor 4 (TLR4) specific signaling inhibitor, reversed muscle atrophy induced by endotoxemia in mice." (PMID 40230720, 2025). "This translocation results in systemic endotoxemia, where lipopolysaccharide (LPS) from Gram-negative bacteria stimulates Toll-like receptor 4 (TLR4) present in immune cells, initiating a state of persistent, low-grade inflammation." (PMID 41226742, 2025).
endotoxemia (continued). "Endotoxemia activates a signaling cascade in which LPS binds to toll like receptor 4 (TLR4) complex, activating the Toll-like receptor 4 (TLR4) and stimulating NF-κB to produce inflammatory cytokines such as tumor necrosis factor-α (TNF-α) and interleukin-1β (IL-1β)." (PMID 40004236, 2025). "Among immune cells, macrophages are responsible for the LPS responses due to several pattern recognition receptors, especially toll-like receptor 4 (TLR-4), on the cell surface, which might be responsible for characteristics of endotoxemia in mice." (PMID 35163596, 2022). "Moreover, it is unclear if the modulations of TLR4 and TNF-α in both the guts and livers of EtOH + Fen-treated mice are a direct effect of Fen on TLR4 signaling, are from reductions in systemic endotoxemia, or both." (PMID 33815111, 2021). "Furthermore, we observed that DOX treatment consistently reduced endotoxemia in DOCA-salt animals, while protecting endothelium-dependent vasorelaxation through down-regulation of TLR4 mRNA, reducing NADPH oxidase activity and ROS levels." (PMID 34578849, 2021). "TLR4 had been considered a gatekeeper of LPS-induced lethality (endotoxemia) and E. coli-induced septic shock, but the non-canonical inflammasome, mediated by caspase-11 in mice or caspase-4/5 in humans, is newly defined as the gatekeeper for the sepsis." (PMID 33154451, 2020). "The present study demonstrated that the pharmacological inhibition of TLR4 reduced skeletal muscle inflammatory and proteolytic pathway activation and reversed muscle wasting in LPS-treated cultured C2C12 myotubes and in mice with endotoxemia." (PMID 31959927, 2020). "TLR4-mediated responses reduce platelet counts in murine endotoxemia, but the role of TLR4 in patients has never been investigated." (PMID 31379873, 2019). "In conclusion, the TLR4 in the terminal ileum of mice with OJ was highly expressed and activated, and massive release of inflammatory factors was induced through the TLR4/TRAF6/NF-κB signaling pathways, which was involved in intestinal mucosal injury and endotoxemia." (PMID 31671112, 2019). "TLR4-mediated and CD40-mediated signals received by macrophages during early endotoxemia are known to promote IL-10 transcription, which can in turn signal to degrade mRNA encoding TNFα, thus identifying IL-10 as a crucial feedback control molecule that mediates cessation of inflammation." (PMID 27125280, 2016). "As a constitutive component of the bacterial cell wall in Gram-negative bacteria, LPS is an important mediator of endotoxemia and its invariant molecular pattern, lipid A, is specifically recognized by Toll-like receptor 4 (TLR4)." (PMID 25955291, 2015). "On characterization of TLR-4 in spleen and thymus of Swiss albino mice—with no reports of TLR-4 expression—induced with endotoxemia, it was found that the mode of expression varied among the organs at both mRNA and protein level in a time-dependent manner." (PMID 25759837, 2015). "Toll-like receptor 4 (TLR4) is induced by hepatocyte-specific transgenic (Tg) expression of the HCV nonstructural protein NS5A, and this induction mediates synergistic liver damage and tumor development by alcohol-induced endotoxemia." (PMID 21331379, 2010). "Dietary lipids facilitate LPS incorporation into chylomicrons and TLR4 is responsible for phagocytosis of gram-negative bacteria by gut enterocytes, each contributing to postprandial endotoxemia." (PMID 20814545, 2010). "In addition, in LPS-induced endotoxemia mice, the expression levels of AST, ALT, and sCr in the peripheral blood were lower in KO mice compared to WT mice, while the overexpression of TLR4 resulted in corresponding increases in the expression levels of these organ injury markers." (PMID 39455728, 2024). "In addition, SFAs act as non-microbial agonists of TLR-4, sharing a common mechanism of action with lipopolysaccharide (LPS), a constituent of intestinal bacteria related to endotoxemia." (PMID 36235574, 2022).
endotoxemia (continued). "However, the survival rate, the severity of endotoxemia, percentage of platelet-neutrophil and platelet-lymphocyte aggregation, platelet P-selectin, CD40L, TLR4 expression, organ injury, tissue perfusion, and biochemical variables were not significantly different among groups B, C, and D." (PMID 35464001, 2022). "However, there have been no previous reports of the impact of pharmacological TLR4 inhibition on skeletal muscle wasting and function during endotoxemia." (PMID 31959927, 2020). "Overexpression of HCV non-structural protein NS5A and induction Toll-like receptor 4 (TLR4) by alcohol-induced endotoxemia in hepatocyte synergistically generates liver damage and tumor development, resulting in the generation of Nanog-positive TICs from the mice model." (PMID 31058850, 2019). "What is required to induce CNS inflammatory responses during endotoxemia is the expression of toll-like receptor 4 (TLR4) on non-hematopoietic, intracranial resident cells located in the leptomeninges, choroid plexus and CVOs, cells along blood vessels, ependymal cells, and parenchymal microglia." (PMID 28154566, 2017). "However, our data suggest that platelet TLR-4 does not induce intrinsic differences in aggregation to account for its role in promoting microvascular thrombosis in endotoxemia." (PMID 22911769, 2012). "Therefore, since both HIV viremia and low level endotoxemia are likely to be persistently present in blood of HIV infected subjects, with each appearing to have an opposing effect on TLR4 levels, one could expect an altered TLR response in HIV infection." (PMID 19461969, 2009). "However, over time, endotoxemia contributed by differences in gut microbial dysbiosis among lean-MAFLD but not healthy individuals or overweight/obese-MAFLD patients results in alterations in the epigenomic and transcriptome including upregulation of Toll-Like Receptor 4 (TLR4)." (PMID 40087205, 2025). "For instance, platelet TLR4 has been shown to promote neutrophil activation and NET formation in endotoxemia and Gram-negative bacterial sepsis." (PMID 40226627, 2025). "To validate the interaction of OGN with TLR4 in vivo, we reasoned that a lack of OGN on circulating leukocytes in OGN null mice, may alter TLR4 signaling in the mouse model of endotoxemia." (PMID 27878326, 2017).
COVID-19 (231 papers, 2020 to 2026). A disease caused by infection with severe acute respiratory syndrome coronavirus 2. "In NK cells, we identified COVID-19 severity-associated genes relating to the TLR4 and TLR9 signaling pathways and to the oncostatin M pathway." (PMID 40532694, 2025). "TLR4, a critical receptor for bacterial lipopolysaccharide (LPS), has been implicated in the hyperinflammatory state of severe COVID-19." (PMID 41176818, 2025). "From March 11, 2020, to June 30, 2021, 1570 SARS-CoV-2 positive patients were enrolled and evaluated to determine the association between the rs4986790 SNP in the TLR4 gene and the severity of COVID-19." (PMID 38433829, 2024). "This study indicated that the TLR4 expression levels were higher in the peripheral blood monocytes of COVID-19 patients with associated CRS than in healthy controls and revealed potential therapeutic drugs for targeting TLR4." (PMID 38165854, 2024). "Specifically, we observed that the AG or GG genotype of rs4986790 in the TLR4 gene was associated with protection against hospitalization, intensive care or death from COVID-19." (PMID 38433829, 2024). "The TLR4 rs4986790 AG/GG genotype reduced by half the risk of COVID-19 patients requiring hospitalization, intensive care or to have a fatal outcome." (PMID 38433829, 2024). "The expression of the IL1B gene in COVID-19 patients is closely associated with the TLR4 signaling pathway." (PMID 39622956, 2024). "In this study, we specifically investigated the single nucleotide polymorphism (SNP) rs4986790 in the TLR4 gene to identify a universal marker for preclinical prediction of COVID-19 disease progression." (PMID 38433829, 2024). "Previously, two other groups investigated the SNP TLR4 rs4986790 and its association with COVID-19 severity." (PMID 38433829, 2024). "The correlation between TLR4 dimerization and activation with pathogenicity of the SARS-CoV-2 variants indicate TLR4 as a potential therapeutic target for treatment of COVID-19." (PMID 38791489, 2024). "Augmented TLR4 expression in COVID-19 has been linked to viral protein interactions, NF-κB activation, and cardiac complications like hypertrophy, inflammation, and fibrosis." (PMID 38022594, 2023). "ROC curve was used also to assess the accuracy of the association between the increase of serum IL-10 and TLR-4 and the presence of lymphopenia among COVID-19 patients." (PMID 36864077, 2023). "Several TLRs (TLR1, TLR2, TLR4, etc.)have an association with disease progression in patients with COVID-19." (PMID 37158916, 2023). "In contrast, a deficient interferon response associated with low levels of TLR-4 has been proposed as one of the relevant mechanisms prompting severe manifestations of COVID-19." (PMID 37283924, 2023). "Similar severe overactivation of the TLR4/NF-κB pathway has been implicated in critical COVID-19 patients." (PMID 37891903, 2023). "The interplay between the spike protein and TLR4, along with the heightened expression of genes linked to TLR4 signaling in COVID-19, underscores a captivating role for these receptors and their inflammatory cascade in disease etiology." (PMID 38022594, 2023). "In COVID-19, the TLR-4/MyD88 axis is activated and associated with the release of pro-inflammatory cytokines and the development of cytokine storm." (PMID 36114383, 2022). "We found two variants in TLR4 gene, already reported in a study of 300 Egyptian patients with a significantly positive risk of severe COVID-19." (PMID 36228008, 2022). "An enhanced TLR4 expression was associated with the COVID-19 SEVERE group when compared to COVID-19 MILD." (PMID 34315957, 2021). "Here, we show that exposure to two 10-min, high-intensity periods per day of infrared light causes a marked reduction in the TLR-4 dependent inflammatory response pathway, which has been implicated in the onset of cytokine storms in COVID-19 patients." (PMID 34552685, 2021).
COVID-19 (continued). "Here, we demonstrate that lower expression of TLR-3 and an enhanced expression of TLR-4 are associated with an unfavorable outcome in COVID-19 patients." (PMID 34315957, 2021). "The other possibility is a secondary mechanism involving damage-associated molecular patterns (DAMPs) released from the lysed or dying cells due to COVID-19, activating TLR4 in the lungs and heart causing inflammation and fibrosis." (PMID 33505220, 2021). "A recent in silico study implicated SARS-CoV-2 activation of Toll-like receptor 4 (TLR4) as a major contributor to the inflammatory response in COVID-19." (PMID 33380345, 2020). "A recent study has confirmed that the coronavirus causing COVID-19 stimulates a TLR4-mediated inflammatory response similar to the pathogenic process of bacterial sepsis." (PMID 33291425, 2020). "TLR-2, TLR-3, and TLR-4 activation by COVID-19 causes the release of inflammatory cytokines such as IL-1β." (PMID 33082858, 2020). "Among the genes encoding molecules involved in innate antiviral immunity such as chemokines and their receptors or TLR, which are associated with the complicated course of COVID-19, fluvastatin directly affected the expression of the TLR4 gene (log2FC = 1.00; p-value ˂ 10−9) in AD-MSC cells." (PMID 40722786, 2025). "Following SARS-CoV-2 infection, TLR4 activation on platelets may be associated with thrombotic events (such as myocardial infarction) in COVID-19 patients, and this thrombosis may affect the kidneys through cardio-renal syndrome." (PMID 40584714, 2025). "In summary, excessive TLR4 activation in COVID-19 patients can trigger NETosis and cause damage to renal tubular epithelial cells, suggesting that TLR4 inhibition could serve as a potential therapeutic target." (PMID 40584714, 2025). "Furthermore, miR-221-3p has been shown to modulate inflammatory responses in M1 and M2 macrophages activated by TLR4, and its dysregulated expression has been reported to be associated with severe COVID-19." (PMID 40806764, 2025). "In conclusion, our data suggest that SARS-CoV-2 S protein-mediated DC-SIGN crosstalk affects TLR4-induced immunity, which might underlie bacterial superinfections during COVID-19." (PMID 37844099, 2023). "Our study shows that in lethal cases of COVID-19 associated lung disease, the inflammatory cells that predominate in the histological picture are TLR-4(+) damaged pneumocytes, with phlogistic infiltration of macrophages, together with lymphocytes and polymorphonuclear neutrophils." (PMID 37686069, 2023). "The results showed that the elevation in levels of serum IL-10 and TLR-4 could be a potential diagnostic marker for lymphopenia in COVID-19 patients with (AUC = 0.66 ± 0.08; P value = 0.05) for IL-10 and (AUC = 0.73 ± 0.07; P value = 0.006) for TLR-4." (PMID 36864077, 2023). "Although these data are limited, in aggregate they suggest that the various forms of AM all share the characteristic of activating both virus-associated (TLR3, TLR7, TLR8 or TLR9) and bacteria-associated (TLR2 and TLR4) innate receptors with severe COVID-19, KD and MIS-C." (PMID 36769320, 2023). "Also, ROC curve showed accurate association between the increase of serum IL-10 and TLR-4 and lymphopenia among COVID-19 patients with AUC = 0.66 ± 0.08 and AUC = 0.73 ± 0.07 respectively." (PMID 36864077, 2023). "The blocking of S100A12 from binding to TLR4 may inhibit the downstream pro-inflammatory signal and is therefore of potential value for designing effective therapeutics against COVID-19-associated acute necrotizing encephalopathy." (PMID 37848421, 2023). "In addition, EGCG mitigated a cytokine storm in COVID-19 by downregulation of TLR4 and NF-κB and alleviated COVID-19-associated complications, such as sepsis, thrombosis, or lung fibrosis." (PMID 36613784, 2022). "It was also revealed that TLR4 genetic polymorphisms might be associated with a severe form of COVID-19 and in-hospital mortalities." (PMID 35538443, 2022).